KRAS (KRas proto-oncogene, GTPase)
Diseases named in the same sentence as KRAS in open-access papers (continued):
Sharing a sentence is not in itself a finding about the gene and the disease.
colorectal cancer (continued). "Ion Torrent sequencing has been recently used to assess RAS status of colorectal carcinoma tumors in the CAPRI-GOIM clinical trial, and a panel of well-known predictive markers in the receptor tyrosine kinase pathway, including KRAS and NRAS, has been developed by the OncoNetwork Consortium." (PMID 26573425, 2016). "In contrast to these findings, colorectal cancer cell sensitivity to treatment is independent of KRAS status and Noxa levels are not up-regulated in the presence of mutated KRAS despite the fact that ERK2 still promotes Noxa expression." (PMID 26028667, 2015). "KRAS and BRAF are major oncogenic drivers of colorectal cancer (CRC)." (PMID 26299805, 2015). "KRAS and NRAS mutations have been identified as negative predictive markers for cetuximab and panitumumab efficacy in colorectal cancer." (PMID 26149458, 2015). "Based on these observations, the KRAS/PIK3CA MT molecular subtype was identified as one of particular interest in the evaluation of alisertib and TAK-733, and a total of nine double-mutant colorectal cancer cell lines were selected for further assessment." (PMID 26136684, 2015). "The present study is first to provide data on frequency and type of KRAS and BRAF mutations of colorectal cancer in Albanian population; no data is present in the literature about this incidence." (PMID 25267307, 2014). "In the context of EGFR inhibition in a wild-type KRAS colorectal cancer cell line we show that a lack of TK1 attenuation, and thus similar [18F]-FLT PET, in treated xenografts reflected PI3K-mTOR activity." (PMID 25247710, 2014). "There are no studies in literature regarding the prognostic role of KRAS mutations in TNM stage I and II colorectal cancer." (PMID 25713627, 2014). "Moreover, full exome sequencing of colorectal cancer samples by our group and collaborators revealed coincident GNAS and KRAS mutations in a small cohort of colon tumors, indicating GNAS mutations in colon cancers might also often be accompanied by mutations in KRAS and/or BRAF." (PMID 24498230, 2014). "In a cellular context, we used the human colorectal cancer cell lines HT29 and HCT116 identified without any mutation in KRAS and BRAF." (PMID 24618737, 2014). "Other biomarkers used to help treatment decisions in colorectal cancer include the use of KRAS mutation status as a predictive marker and the use of BRAF mutations as a strong negative prognostic indicator in KRAS wild-type colorectal cancer." (PMID 25566504, 2014). "The absence of both KRAS and BRAF mutations are common features seen in colorectal cancers that are responsive to cetuximab, thus making the EGFR mutation in this case of particular interest." (PMID 24894453, 2014). "Our current data suggest that KRAS mutations, irrespective of mutated codon, are inversely associated with MSI-high and BRAF mutations in colorectal cancer." (PMID 24885062, 2014). "BRAF and EGFR (epidermal growth factor receptor) genes, which are important co-factors of KRAS gene in the EGFR signaling pathway in the carcinogenesis, invasion and metastasis of colorectal cancers, also have prognostic value for patients with metastasis of adenocarcinoma." (PMID 25297496, 2014). "At present, there are no clinical decisions that are impacted by KRAS mutation status in patients with stage I, II, or III colorectal cancer." (PMID 24653752, 2014). "For example, benefits of cetuximab and panitumumab in colorectal cancer and benefits of the EGFR tyrosine kinase inhibitors (TKIs) erlotinib and gefitinib in NSCLC are respectively associated with presence vs absence of KRAS and EGFR mutations." (PMID 23587187, 2013).
colorectal cancer (continued). "Prediction of cetuximab responsiveness for KRAS wild-type colorectal cancers is currently not well defined, and prognostic biomarkers would help tailor treatment to individual patients." (PMID 24152305, 2013). "TRAIL sensitivity was not related to the presence of activating oncogenic KRAS, BRAF and PIK3CA mutations common to colorectal cancer." (PMID 23852390, 2013). "Retrospective analyses in the West suggest that mutations in KRAS codons 61 and 146, BRAF, NRAS, and PIK3CA are negative predictive factors for cetuximab treatment in colorectal cancer patients." (PMID 24006859, 2013). "This suggests that the still-unrecognized “true target” for panitumumab (and cetuximab) is present in 30-40% of KRAS wild-type colorectal cancers, and in almost no KRAS-mutant colorectal cancers." (PMID 23587187, 2013). "PTEN status was not prognostic for survival in advanced colorectal cancer, irrespective of KRAS or BRAF status." (PMID 23930204, 2013). "All colorectal carcinoma samples had been reported as BRAF and KRAS wildtype by q-PCR sequencing." (PMID 23922754, 2013). "The colorectal cancer model VARI-LTM-026, did not exhibit mutations in the patient tumor, but showed a single KRAS mutation in the tumorgraft." (PMID 22709571, 2012). "In contrast to KRAS, the heterogeneity of BRAF and PIK3CA mutations has not been adequately investigated in colorectal cancer thus far." (PMID 22931052, 2012). "There is evidence that KRAS mutations are highly specific negative prognostic factors of response (de novo resistance) to EGFR-targeted therapy in both NSCLC and colorectal cancer." (PMID 21792199, 2011). "KRAS does not seem to be a predictive factor in a study with Gefitinib and chemotherapy for advanced colorectal cancer." (PMID 21197450, 2010). "In colorectal cancer (CRC) cell lines SW480, HT-29 and Caco2, miR-16 inhibits tumor proliferation and metastasis of tumor cells by restoring Sensitivity to Tyrosine Kinase inhibitors, and targeting the transcription of 3′ untranslated regions (3′ UTRs) of KRAS and inhibiting KRAS's expression." (PMID 40061926, 2025). "Sotorasib plus panitumumab, according to an approach of dual KRAS G12C and EGFR blockade, overcame treatment resistance in patients with colorectal cancer with KRAS G12C mutation, typically a population not responding to EGFR inhibitors, such as cetuximab and panitumumab." (PMID 39941081, 2025). "For example, in colorectal cancer (CRC), tumor-derived lanosterol can be taken up by CD8+ T cells, where it suppresses the mevalonate pathway and reduces prenylation and activity of KRAS proto-oncogene, GTPase (KRAS), ultimately promoting T cell apoptosis and impairing their antitumor function." (PMID 40659633, 2025). "Similarly, in colorectal cancer, ADM is among the most selectively upregulated genes in KRAS-mutant cells under hypoxia, and its expression is markedly reduced upon KRAS silencing, highlighting ADM as a key downstream effector of KRAS-driven tumorigenesis in hypoxic niches." (PMID 40547013, 2025). "Most cancers with atypical KRAS mutations (291/335, 86.9%) had no additional mutations in BRAF, NRAS, or NF1, with the incidence of these mutations being far lower than the incidence of concomitant Ras mutations in atypical BRAF colorectal cancers." (PMID 39751654, 2025). "However, as a human homologous gene of IRE1, knockout of ERN1 (endoplasmic reticulum to nucleus signaling 1) in KRAS-mutant colorectal cancer cells does not affect cell growth but does sensitize the cells to MEK inhibition." (PMID 38275900, 2024).
colorectal cancer (continued). "The presence of KRAS and NRAS mutations indicates a different mutation spectrum in the rectum, which might be more associated with sporadic colorectal cancers rather than hereditary syndromes such as Lynch." (PMID 39768914, 2024). "Interestingly, these include not only classical KRAS-driven malignancies such as lung, pancreatic and colorectal cancer, but also mammary neoplasms which are not known to harbour KRAS mutations." (PMID 39179604, 2024). "Interestingly, KRAS mutations are not detected in early colon adenomas, and are instead detected after APC mutations in late adenomas during the development of colorectal carcinomas." (PMID 38474205, 2024). "PDXEDEPMAP also detected markedly stronger KRAS essentiality in KRAS-mutant PDX of pancreatic ductal carcinoma (PDAC) and colorectal carcinoma (CRC) lineages, whereas BRAF essentiality was strongest in BRAF-mutant PDX of cutaneous melanoma (CM)." (PMID 39009815, 2024). "Moreover, increasing ERK activity in colorectal cancer cells induced the EMT fate irrespective of their KRAS status." (PMID 38201521, 2023). "However, unlike the case of BRAF-mutated colorectal cancer, our combination of lapatinib and SHP099 integrated 2 different targets both upstream of KRAS and did not require MEK- or RAF-directed agents." (PMID 36752207, 2023). "Likewise, it has been reported that exosomes from KRAS mutant colorectal cancer (CRC) cells transfer mutant KRAS to nonmutated cells enhancing three‐dimensional growth." (PMID 36168102, 2023). "Furthermore, gastrointestinal cancers, such as colorectal cancer, gastric cancer, pancreatic cancer, and bile duct cancer, were related to low recommendation rates (<20%), wherein ERBB2 amplification, KRAS G12C, and microsatellite instability (MSI)‐High (MSI‐H) resulted in recommendations commonly." (PMID 36251535, 2023). "Moreover, as KRAS gene testing was carried out relatively late in this unit, the relationship between MIS status and KRAS mutations and their prognosis with colorectal cancer were not studied." (PMID 38348120, 2023). "Interestingly, the analysis of immune cell populations suggests a propensity for neutrophil recruitment to BRAF/KRAS mutant CRLM in the absence of APC mutations, corroborating observations from serrated colorectal cancer murine models in human patients." (PMID 37057593, 2023). "Increasing copy number of Fn is associated with a higher probability of colorectal cancer with MLH1 hypermethylation (OR: 1.56, P < 0.0001), MSI-H (OR: 1.5, P < 0.0001), and BRAFV600E (OR: 1.33, P = 0.027), but not with KRAS mutations (OR: 1.15, P = 0.113) in univariate logistic regression analysis." (PMID 37772997, 2023). "Interestingly, KRAS oncogenic mutations were frequently found in colorectal cancer cell lines showing high levels of both DX2 and KRAS, while no clear correlation was observed between KRAS level and mutations in lung and pancreatic cancer cell lines." (PMID 35546148, 2022). "Some studies have not found KRAS codon 61 mutations in the young patients with NSCLC, and indicated that the incidence of codon 61 mutation was more frequent in the older patients with colorectal cancer." (PMID 35031014, 2022). "KRAS oncogenes have been identified in a quarter of all human tumors and appear with high prevalence in some of the most lethal types of cancer such as pancreatic ductal adenocarcinoma (PDAC, 95%), colorectal carcinoma (CRC, 50%), and lung adenocarcinoma (LUAD, 30%)." (PMID 36383067, 2022).
colorectal cancer (continued). "A total of 211 advanced colorectal cancer patients were enrolled in a phase II study, and were divided into 3 arms(arm A: EZN-2208, for KRAS-mutant patients; arm B: EZN-2208+cetuximab, for KRAS-wild-type patients; arm C: irinotecan+cetuximab, for KRAS-Wild type patients)." (PMID 35004308, 2021). "IMO is a novel second-generation, modified, immunomodulatory TLR9 agonist and was proven to synergistically inhibit tumour growth by improving the ADCC activity of cetuximab in a cetuximab-resistant colorectal cancer line and a mouse model regardless of KRAS genotype." (PMID 34663410, 2021). "This study displayed a significantly lower rate of KRAS wild‐type in pancreatic body/tail cancers than pancreatic head cancers, indicating a low efficiency of regorafenib, panitumumab and cetuximab, which are FDA‐approved drugs for the treatment of colorectal cancer patients with KRAS wild‐type." (PMID 33452856, 2021). "In addition, the direct KRAS G12C inhibitor AMG 510, which will be described more in the lung and pancreatic cancer sections, has also showed great promise in reducing tumor size in colorectal cancer patients." (PMID 33801965, 2021). "In light of our new findings, it is likely that molecularly targeted therapies, such as KRAS inhibitors, BRAF inhibitors, angiogenesis inhibitors, and immune checkpoint inhibitors, should be validated for treating advanced-stage duodenal adenocarcinoma, similar to the studies of colorectal cancer." (PMID 34797780, 2021). "Interestingly, PI3K activation in KRAS-mutant lung and colon cells is dependent on insulin-like growth factor 1 receptor (IGF1R) activity and a combination of MEK and IGF1R inhibitors showed synergistic effects both in NSCLC and colorectal cancer (CRC)." (PMID 34200676, 2021). "A positive crosstalk between the activity of tyrosine kinases/KRAS/ERK and WNT/β-catenin would result in the hyperinduction of the transcriptional activity of Wnt/β-catenin above optimal levels for cell proliferation, favoring the apoptotic process in colorectal cancer cells." (PMID 34577571, 2021). "It has been hypothesized that this inconsistency in the tumor response could be due to KRAS G12C not being the dominant oncogenic driver in colorectal cancer." (PMID 34781949, 2021). "Furthermore, knocking down STAT3 in mutant KRAS colorectal cancer cells, but not wild‐type KRAS cells resulted in enhancement of cells’ response to oxaliplatin and 5‐FU." (PMID 33274592, 2021). "To identify a highly effective but a low toxicity treatment for KRAS-mutant cancers, here we investigate the effect of FMD in potentiating the anticancer activity of vitamin C, alone or in combination with standard chemotherapy with a focus on colorectal cancer (CRC)." (PMID 32393788, 2020). "Likewise, Ser181 phosphorylation of oncogenic KRas was involved in tumour growth after subcutaneous injection of NIH3T3 fibroblasts or the colorectal cancer cell line DLD1 stably expressing phosphomimetic and non-phosphorylatable KRas mutants in nude mice." (PMID 32456244, 2020). "Altogether, data from colorectal cancer and NSCLC suggest that p65BTK is an emerging actionable target in tumour cells resistant to chemotherapy and scarcely responsive to target therapy because of lack of EGFR mutation or presence of activated KRAS." (PMID 31200752, 2019). "To examine the basal levels of autophagy in colorectal cancer (CRC) cell lines, we selected the human RKO cell line and primary SW480 and its derivative metastatic SW620 cell lines as representative of a range of BRAF-driven and KRAS-driven colorectal genotypes, respectively." (PMID 31151160, 2019). "In a large cohort of 85 patient-derived colorectal cancer xenografts, Bertotti and colleagues identified HER2 gene amplification in some xenografts, which were resistant to cetuximab and did not harbour mutations in KRAS, NRAS or BRAF genes." (PMID 31164152, 2019).
colorectal cancer (continued). "Contrarily to ERBB2, KRAS is not a target of the mAbs used in colorectal cancer." (PMID 31169290, 2019). "Given the improved affinity of the KRAS4b-PDEδ complex through binding of C19, and the importance of this complex in certain types of colorectal cancer, we wanted to know whether C19 affects the viability of KRAS-dependent colorectal cancer cells." (PMID 30382908, 2018). "RAPTOR dysregulation was also implicated in a study of colorectal cancer: compared with cells that were either mutant or wild-type for both KRAS and PIK3CA, non-isogenic KRAS-mutant cells were reported to be relatively resistant to mTOR kinase inhibitor PP242, and to modestly overexpress RAPTOR." (PMID 29389967, 2018). "Moreover, dMMR, KRAS and NRAS mutation were not prognostic factors for stage I–III colorectal carcinoma." (PMID 29423347, 2018). "Multivariate analysis showed that NDRG4 could be a prognostic factor for overall survival of patients with colorectal cancer independent of gender, age, differentiation status, TNM stage, KRAS, BRAF and PIK3CA mutations and MSI status." (PMID 26515606, 2016). "Finally, it can result in MSS, CIN-H, CIMP-negative colorectal cancer with no mutations in BRAF and KRAS." (PMID 27276710, 2016). "Multivariate analysis showed that NEAT1 expression could be a prognostic factor for overall survival of patients with colorectal cancer independent of gender, age, differentiation status, TNM stage, MSI, KRAS, BRAF and PIK3CA mutation." (PMID 26314847, 2015). "Colorectal cancer patients with PIK3CA and KRAS mutations did not respond to therapy." (PMID 26404261, 2015). "Instead of contradicting the importance of KRAS variability in the treatment of NSCLC, the different prognostic values of KRAS mutations in colorectal cancer versus NSCLC only confirm the need to determine how non-EGFR genetic variations affect the outcome of cetuximab treatment." (PMID 25962919, 2015). "However, the preclinical and clinical performance of an NGS system for the detection of gene sets including minor mutations in KRAS, NRAS, and BRAF in patients with colorectal cancer has not been previously reported." (PMID 25954997, 2015). "In the present study, we analyzed the impact of KRAS status, determined by both direct sequencing and PNA-PCR methods in tumor and matched plasma samples, on clinical outcome in a large consecutive mono-institutional series of advanced colorectal cancer patients." (PMID 25491325, 2014). "Of the 10 patients with cancers other than colorectal and FBXW7 mutations, none (0%) had simultaneous KRAS mutations or APC mutations compared to 6/7 (86%) patients with KRAS mutations and 3/7 (43%) with APC mutations in the colorectal cancer group (p = 0.0006 and p = 0.022)." (PMID 24586741, 2014). "However, despite these advancements, it is clear that not all colorectal cancer patients with wild-type KRAS would gain benefit from anti-EGFR mAbs and objective responses have also been reported in patients with KRAS mutated tumours." (PMID 24609222, 2014). "A KRAS A146 mutation assay was included on the MALDI-TOF panel and no mutations were detected, consistent with previous reports suggesting this particular mutation, although relevant in colorectal cancer, is not important in NSCLC." (PMID 24956168, 2014). "The recognition that colorectal cancer (CRC) is a heterogeneous disease in terms of clinical behaviour and response to therapy translates into an urgent need for robust molecular disease subclassifiers that can explain this heterogeneity beyond current parameters (MSI, KRAS, BRAF)." (PMID 23836465, 2013).